TJP2 (tight junction protein 2)
Diseases named in the same sentence as TJP2 in open-access papers (continued):
Sharing a sentence is not in itself a finding about the gene and the disease.
liver cancer (2 papers, 2021 to 2022). An epithelial or non-epithelial malignant neoplasm that arises from the liver. "Many studies have reported that infant liver cancer patients have TJP2 gene variants." (PMID 34504838, 2021). "In Western countries, pediatric liver cancers were reported to occur in patients with PFIC; notably, 5–15% of children with PFIC2 present HCC early, from 13 to 28 months of age, but several cases are well described in infants with TJP2 disease (PFIC4) and MDR3 deficiency (PFIC3)." (PMID 35884482, 2022).
lung adenocarcinoma (2 papers, 2013 to 2023). A carcinoma that arises from the lung and is characterized by the presence of malignant glandular epithelial cells. "TJP2 protein and/or mRNA expression is either lost or decreased in pancreatic, prostate, breast and lung adenocarcinomas, in testicular in situ carcinoma and in lung squamous carcinoma." (PMID 24267658, 2013).
melanoma (2 papers, 2015 to 2024). A malignant, usually aggressive tumor composed of atypical, neoplastic melanocytes. "In this study, we successfully generated Tjp1 and Tjp2 KO melanoma cells for the first time using the CRISPR/Cas9 system and demonstrated that TJ proteins are not only important for barrier function but also have a significant effect on cancer progression." (PMID 38255907, 2024). "In this study, we first knocked out Tjp1 and Tjp2 in B16-F10 mouse melanoma cells using the CRISPR–Cas9 system and analyzed the tumorigenic characteristics, such as invasion and migration, in vitro." (PMID 38255907, 2024). "We further investigated whether Tjp1 and Tjp2 KO stimulated the metastatic potential of B16-F10 melanoma cells." (PMID 38255907, 2024). "In HUVECs co-cultured with melanoma cells there was a marked decrease in expression levels of several endothelial markers (KRT7, KRT18, TJP2), as well as a severe decrease in FST expression, an EMT/EndMT antagonist." (PMID 25742314, 2015). "We examined the effects of Tjp1 and Tjp2 KO expression on tumor growth and metastasis by subcutaneously and intravenously injecting separate groups of mice (10 per test group) with MOCK, Tjp1 and Tjp2 KO, or Tjp1 and Tjp2 re-expressed B16-F10 melanoma cells." (PMID 38255907, 2024).
myopia (2 papers, 2013 to 2023). "By using a GWAS approach, SNPs near TJP2, PCBP3, CADM2, and TRPM3 were identified to be associated with myopia or refractive errors, and HMG20A and PPP2R2B were associated with axial length and corneal astigmatism, respectively." (PMID 37449273, 2023).
autosomal dominant deafness 51 (1 paper, 2025). "Both increased expression and decreased stability of TJP2 have been linked to autosomal dominant deafness 51 (DFNA51)." (PMID 40121402, 2025).
Chronic colitis (1 paper, 2023). A chronic inflammatory disease of the large intestine (colon, cecum and rectum). "Jam2 and Ocln mRNA expression was significantly increased in both wildtype and Muc13−/− mice upon acute and chronic colitis, respectively, whereas Tjp2 mRNA expression was only elevated in Muc13−/− mice after the first DSS cycle." (PMID 37174625, 2023).
cryptorchidism (1 paper, 2025). The failure of one or both testes of a male fetus to descend from the abdomen into the scrotum during the late part of pregnancy. "The results showed that six target proteins of TJP2, ZO-1, SYNPO2, SYNPO, LMCD1, and MCU showed characteristic distribution in the epididymal tissues of the cryptorchidism group and the normal control group." (PMID 41217791, 2025).
endothelial dysfunction (1 paper, 2025). In vascular diseases, endothelial dysfunction is a systemic pathological state of the endothelium (the inner lining of blood vessels) and can be broadly defined as an imbalance between vasodilating and vasoconstricting substances produced by (or acting on) the endothelium. "Loss of methylation in genes such as TJP2 (zona occludens 2) has been associated with endothelial dysfunction and increased permeability, facilitating aortic wall disruption and dissection progression." (PMID 40305299, 2025). "For example, zona occludens proteins ZO-1 and ZO-2 (encoded by TJP2) have been found to be underexpressed in thoracic aortic dissection (TAD), leading to endothelial dysfunction and exacerbating wall instability." (PMID 40305299, 2025).
familial hypercholanemia (1 paper, 2015). "CLDN1 and TJP2 encode integral TJ proteins; mutations in CLDN1 were found in neonatal ichthyosis-sclerosing cholangitis syndrome (NISCH) and TJP2 mutations cause familial hypercholanemia (FHC) and a newly described subtype of Progressive Familial Intrahepatic Cholestasis syndrome (PFIC-4)." (PMID 26116792, 2015).
liver failure (1 paper, 2022). A liver disease characterized by the liver losing or has lost all of its function. "Newborns with TJP2 deficiency present with jaundice, pruritus, and progressive intrahepatic cholestasis and eventual liver failure and juvenile hepatocellular carcinoma." (PMID 35284810, 2022).
long-QT syndromes (1 paper, 2025). "Several variants in the L-type calcium channel component CACNA1C have also been demonstrated to predispose for arrhythmic phenotypes, especially long-QT syndromes, while the gap junction protein encoded by TJP2 has been associated with hypertrophy in other cell types." (PMID 40791945, 2025).
microvillous inclusion disease (1 paper, 2025). "This led to the discovery of three new conditions; PFIC 4, 5, and 6, caused by mutations in TJP2 (tight junction protein 2), NR1H4 (farnesoid X receptor), and MYO5B (linked to microvillous inclusion disease), respectively." (PMID 39927143, 2025).
pancreatic cancer (1 paper, 2024). "Tjp2 may represent a novel target for molecular therapies aimed at preventing the invasion and metastasis of hamster pancreatic cancer." (PMID 38255907, 2024).
renal carcinoma (1 paper, 2025). A carcinoma arising from the epithelium of the renal parenchyma or the renal pelvis. "Among 15 genes which downregulated in Ureteral sample, as well as the chromatin states closed in their potential regulatory sites, four genes (CEP170B, CHMP4C, KCNN4, and TJP2) are prognostic for renal cancer, that high expression is favorable." (PMID 40034749, 2025).
scleroderma (1 paper, 2022). Scleroderma is a rare autoimmune connective tissue disorder characterized by abnormal hardening of the skin and, sometimes, other organs. "However, mesenchymal–epithelial transition (MET) associated proteins such as SCRIB, DSP, TJP1, CDH1, DLG1, and TJP2 were downregulated in scleroderma skin, indicating the high severity of skin fibrosis in mice with scleroderma." (PMID 35315234, 2022).
tumor (28 papers, 2006 to 2025). "Mechanistic studies have shown that CLDN6 promotes tumor progression via the CLDN6/tight junction protein 2 (TJP2)/yes-associated protein 1 (YAP1) axis, activating the Hippo signaling pathway." (PMID 41425250, 2025). "By analyzing TCGA-KIRC data, results also indicated that TJP2 is also significantly decreased in ccRCC and decreased TJP2 expression is associated with higher tumor grade and stage, distant metastasis and poor prognosis." (PMID 36966163, 2023). "Decreased TJP2 expression is associated with higher tumor grade and stage." (PMID 36966163, 2023). "After comparing the mean tumor sizes of all treatment groups, we discovered that tumor growth was significantly increased in the Tjp1 and Tjp2 KO injected groups and growth rates recovered in the Tjp1 and Tjp2 re-expressing groups." (PMID 38255907, 2024). "Among these proteins is TJP2 (also called ZO-2), which is an important regulator in tumor growth and metastasis." (PMID 34650982, 2021). "TJP2 is a candidate tumor suppressor and overexpression of TJP2 will block the cell cycle and inhibit cell proliferation." (PMID 24564989, 2013). "For example, the tight junction protein 2 (ENSG00000119139, TJP2) has been proposed to be a tumor suppressor gene." (PMID 24267658, 2013). "TJP1 (ZO-1) and TJP2 (ZO-2) proteins were also expressed by the majority of progenitor and stem cells from tumor cell cultures, whereas only a minority of the total cell population expressed PAPPA." (PMID 18492237, 2008). "TJP2, also known as ZO-2, is a tight junction protein and a known tumor suppressor gene." (PMID 41187747, 2025). "TJP2 function is down-regulated in various tumor types, which could suggest a direct involvement in carcinogenesis." (PMID 39697951, 2024). "Additionally, we analyzed the effects of Tjp1 and Tjp2 KO on tumor growth and experimental metastasis in an in vivo model." (PMID 38255907, 2024). "Furthermore, the mean tumor size was 14.5 mm (95% CI_ 9.37 to 20.6 mm) for mice injected with Tjp2 KO B16-F10 cells and 12.8 mm (95% CI_ 9.94 to 20.23 mm) for mice injected with Tjp2 re-expressed B16-F10 cells." (PMID 38255907, 2024). "In summary, tumorigenic characteristics, including cell proliferation, migration, invasion, tumor growth, and metastatic potential, were significantly increased in Tjp1 and Tjp2 KO cells, and the knockout of Tjp genes significantly affected the expression of related proteins." (PMID 38255907, 2024). "It has been suggested that TJP2 may, in fact, have a role as a tumour suppressor gene." (PMID 36010647, 2022). "However, correlation does not imply causation, and the mere association between aberrant TJP2 expression and cancer is not in itself evidence of a tumour suppressor effect." (PMID 36010647, 2022). "For example, the TJP2 and OXTR genes showed haplotype-biased methylation upregulation, resulting in the downregulation of their mRNAs in the tumor regions." (PMID 41187747, 2025). "The analysis of tumor tissue by immunohistochemistry showed a high expression of tight junction proteins PARD3, TJP2, and occludin (OCLN) in subcutaneous tumors formed by Nrp2−/− CRC organoids." (PMID 35158941, 2022). "Furthermore, after knocking down TJP2 expression based on ZNF582 overexpression, the tumor growth rate is significantly restored." (PMID 36966163, 2023). "In addition, among our top 50 dysregulated phosphoproteins were cortactin and tight-junction protein-family protein (TJP2, or ZO-2) as well as AHNAK1, known to be involved in tumor metastasis through EMT." (PMID 35977930, 2022). "In our results, a hypermethylated gene, SOX1 expression reduced in tumor tissue, whereas TJP2 expression did not reduce." (PMID 23735005, 2013).
cancer (19 papers, 2008 to 2025). A tumor composed of atypical neoplastic, often pleomorphic cells that invade other tissues. "In humans, Tjp1 and Tjp2 are known to play a role in the invasion and metastasis of cancer by regulating the expression of Tjp1 and Tjp2 and causing changes in barrier function due to structural alterations in tight junctions." (PMID 38255907, 2024). "Furthermore, Tjp1 and Tjp2 are reported to be associated with several diseases, including cancer, autoimmune disorders, and gastrointestinal disorders." (PMID 38255907, 2024). "In conclusion, Tjp1 and Tjp2 play a significant role in cell proliferation, migration, cancer growth, and metastasis, involving various genes." (PMID 38255907, 2024). "Using bioinformatics analysis, we further found that the tight junction proteins TJP1 and TJP2 show significant positive correlations with SPIN4 and are linked to cancer cell survival." (PMID 34575061, 2021). "Some of the upregulated genes are related to CSC/’cancer stemness’ such as CXCR4, CD133, EPCAM and SOX9, while others are associated with apoptosis (FASLG, TJP2, DUSP4), the MAPK pathway (MAP2K4, DUSP4), and chemoresistance (MMP1, an ETS1 target gene)." (PMID 24069258, 2013). "While Program-1 was enriched with genes from a pan-cancer EMT program, it also notably included epithelial differentiation genes such as CDH1, IRF6, JUP, KLF6, and TJP2." (PMID 40777467, 2025). "Next, by examining the DNA copy numbers of the TJP family in multiple cancer cell lines, we observed that the DNA copy numbers of TJP1, TJP2, and TJP3 were upregulated in 10, 9, and 7 different cancer cell lines, respectively." (PMID 35087173, 2022). "By evaluating the mRNA expression of TJP1, TJP2, and TJP3 in 40 different cancer cell lines, we found that TJP1, TJP2, and TJP3 were upregulated in 29, 40, and 12 different cancer cell types, respectively." (PMID 35087173, 2022). "Aberrant expression of TJP2 has also been noted in nonliver cancers." (PMID 36010647, 2022).
infection (10 papers, 2014 to 2026). The state of being infected such as from the introduction of a foreign agent such as serum, vaccine, antigenic substance or organism. "The mRNA expression of TJP1, TJP2, and ZO-1, which are associated with the intestinal permeability barrier, were affected by the PAstV1 infection." (PMID 31847270, 2019). "TJP2 was also positively regulated, while GPRC5C was negatively regulated 90 min post-infection." (PMID 25101063, 2014).
genetic disorders (1 paper, 2018). "In the last 5 years, new genetic disorders, such as TJP2, FXR, and MYO5B defects, have been demonstrated to cause a similar PFIC phenotype." (PMID 30367658, 2018).
TJP2 also shares sentences with these, for which no sentence is quoted: colitis (9 papers); cyst (3); Alagille syndrome (2); brain tumors (2); inflammation (2); inflammatory bowel disease (2); alcoholic fatty liver (1); allergies (1); aneurysm (1); bile duct carcinoma (1); breast adenocarcinoma (1); cardiac diseases (1); cholangiocarcinoma (1); choroidal neovascularization (1); Ciliary Dyskinesia (1); clear cell renal cell carcinoma (1); coccidiosis (1); colon carcinoma (1); colon tumor (1); colonic adenocarcinoma (1); conjunctivitis (1); Corneal astigmatism (1); coronary artery disease (1); COVID-19 (1); Cyanosis (1); cystitis (1); dengue (1); diabetes (1); diabetic retinopathy (1); E. coli infection (1).
A further 44 diseases each share a sentence with TJP2 in 1 paper.